IFNG (interferon gamma)
Diseases named in the same sentence as IFNG in open-access papers (continued):
Sharing a sentence is not in itself a finding about the gene and the disease.
tumor (continued). "A remarkable immunomodulatory effect was reflected by the augmentation of IL-2, 6, 12, Tumor necrosis factor-α (TNF-α), and interferon-gamma (IFN-γ) productions from the spleen lymphocytes of C. versicolor-treated tumor-bearing mice." (PMID 28885559, 2017). "Concomitantly, the expression of PD-1 ligands PD-L1 and PD-L2 in tumor cells is induced by cytokines and inflammatory factors, such as interferon gamma (IFNγ), mostly secreted by activated T cells infiltrated in the tumor." (PMID 28545238, 2017). "Upon treatment, CD4+ T cells are recruited in the tumors, enhance and maintain CD8+ T cell activation, and induce MHC-II expression on tumor cells through the release of IFNγ, leading to their recognition and death." (PMID 29403144, 2017). "Through this study we evaluated a broad selection of pediatric tumor cells, representing at least six different types of malignancies, for the effect of IFNγ on their sensitivity to NK cell-mediated lysis using expanded NK cells from four independent donors." (PMID 28428785, 2017). "Here we report the generation of anti-tumor immune responses by beDCs and their conversion into immune-organoids capable of inducing IFNγ-secreting activated lymphocytes." (PMID 27223090, 2016). "IFNγ probably plays a minor or an upstream role since double knockout (KO) mice are resistant to tumor cell growth like IL-17−/−." (PMID 27589729, 2016). "Our data provide insight into the possible mechanisms of the anti-tumor activity of IFNγ during the course of immune therapy and demonstrate for the first time an essential role for IDO as a mediator of IFNγ-induced apoptosis of HNSCC cells." (PMID 27486476, 2016). "The PD-1/PD-L1 pathway that affords tumor immune evasion is an adaptive resistance mechanism in which PD-L1 expression is induced in the tumor microenvironment by IFNγ producing T cells (TILs)." (PMID 26910562, 2016). "IFNγ is a canonical M1-polarizing cytokine and it prevents tumor development and reverses the M2 phenotype of TAMs." (PMID 26799669, 2016). "It is also a well-known fact that STAT activation is generally mediated by members of the JAK family of tyrosine-kinases via stimulation of NF-κB regulated genes such as IL-6, IL-10 and IFNγ which are produced by tumor cells in an autocrine manner." (PMID 26998758, 2016). "Ad.EPCR treatment elicited recruitment of macrophages and NK cells into the tumor microenvironment and increased IFNγ and TNFα levels in the pleural space." (PMID 27833109, 2016). "The studies in this report show that this is also accompanied by significant upregulation of PD-L1 expression in the tumor microenvironment, a known adaptive resistance mechanism that occurs in response to IFNγ produced by tumor-infiltrating T cells." (PMID 26910562, 2016). "Animals in which complete tumor regression occurred with combination treatments were resistant to secondary tumor challenge and presented heightened expression levels of splenocyte-produced IFNγ." (PMID 27169467, 2016). "The TNFα and IFNγ synergism has been reported under many biological conditions including their tumor inhibitory effect." (PMID 27342639, 2016). "PD-L1 upregulation on tumour cells (including Pan02 cells) and myeloid cells can be induced by IFNγ." (PMID 26918344, 2016). "Immunofluorescence staining showed that TNFα increased both CD8+ cytotoxic and CD4+ helper T lymphocytes inside the tumor while IFNγ increased CD4+ T cell." (PMID 27342639, 2016). "In particular we show that SCIB1 induced IFNγ responses upregulated PD-L1 within the tumor thereby reducing the effectiveness of the vaccine." (PMID 27825115, 2016). "Other studies evaluated tumor-infiltrating immune cells, interferon-gamma, and other factors of the tumor microenvironment." (PMID 26970967, 2016). "Intracellular production of IL-2, TNF and IFNγ by tumor-specific T cells was examined after overnight stimulation with MCC peptide." (PMID 27121060, 2016).
tumor (continued). "In this study, we have demonstrated that co-stimulatory CXCR6/CXCL16 interactions specifically increase IFNγ production following glycolipid activation and lead to enhanced tumor control in vivo following adoptive DC transfer." (PMID 27471636, 2016). "Although the role of IFNγ in the modulation of tumor immunity has been widely documented, the mechanisms regulating IFNγ-induced cell death, during the course of immune therapy, is not described in detail." (PMID 27486476, 2016). "The data demonstrated that targeted delivery of TNFα combined with IFNγ by TCP-1 peptide drastically inhibited tumor growth than single treatment and at the same time alleviated systematic toxicity induced by non-targeted TNFα and IFNγ." (PMID 27342639, 2016). "These tumor-infiltrating, antigen-specific T cells produce multiple cytokines (particularly high amounts of IFNγ and TNFα), exert cytotoxic activity, and improve the Teff:Treg ratio to delay tumor growth." (PMID 26910562, 2016). "The four states of tumor-infiltrating lymphocytes were defined to have a progressive decrease in IFNG gene expression and cytotoxic killing ability." (PMID 28101055, 2016). "NK cells play an important role in tumor surveillance, it exerts anti-tumor function by direct cytotoxicity or cytokine secretion such as IFNγ." (PMID 27556180, 2016). "Collectively, the results suggest a transient disconnect between the extracellular signal, that is TILs release of IFNG, and the tumor response." (PMID 28101055, 2016). "In vivo, antibody blockade and knock-out of IFNG abrogates any benefit of immunization in controlling B16F10 tumor growth." (PMID 28101055, 2016). "Results from various clinical trials, including peptide and whole tumor cell vaccination and cytokine treatment, showed the suitability of the IFNγ ELISPOT assay for monitoring T cell response." (PMID 27234522, 2016). "Poxvirus-based active immunotherapies induce infiltration of antigen-specific T cells to the tumor, which produce large amounts of IFNγ after encountering the cognate tumor-antigen." (PMID 26910562, 2016). "Most interestingly, combination treatment by TCP-1/TNFα and TCP-1/IFNγ dramatically inhibited tumor growth." (PMID 27342639, 2016). "Although no change in MDSC levels was observed, dacarbazine triggered the upregulation of NKG2D ligands on tumor cells, leading to NK cell activation and IFNγ secretion." (PMID 26716894, 2016). "Tumor vasculature targeting approach also has been used to deliver IFNγ to tumor tissues for targeted therapy." (PMID 27342639, 2016). "Recent studies that have shown that blocking glycolytic commitment by pretreating T cells with 2-deoxy glucose (2-DG) also renders the T cells with reduced IFNγ secreting ability, but improved in vivo survival and tumor control." (PMID 27750220, 2016). "Once situated intratumorally, the tumoricidal myeloid precursors can be activated by exogenous TLRa in tandem with IFNγ supplied by the endogenous anti-tumor T-cell response." (PMID 27341020, 2016). "Interferon-gamma (IFN-γ) is a pleiotropic cytokine that exerts anti-tumor and anti-osteoclastogenic effects." (PMID 27573075, 2016). "Primary RMA tumors were dissociated, and tumor-infiltrating T cell populations were stained for intracellular perforin and IFNγ." (PMID 28003813, 2016). "Lastly, we studied natural killer (NK) cell function and found that tumor-infiltrating NK cells from mice fed the KD produce significantly more IFNγ and TNF in response to GL261-Luc2 cells than the cells isolated from SD fed animals." (PMID 27178315, 2016). "Both the CT26-HER-2 and MC38-MUC1 murine tumor cell lines up-regulate PD-L1 in response to IFNγ in a dose-dependent manner." (PMID 26910562, 2016). "In adaptive immune resistance, PD-1 ligands are overexpressed on tumor cells in response to cytokines, in particular IFNγ." (PMID 28018902, 2016).
tumor (continued). "Levels of IL-12 remained unchanged in both LLC and B16F10 tumours although B16F10 tumours showed stimulation of all other cytokines evaluated while LLC only showed increased levels of IFNγ and IL-1β compared to untreated controls." (PMID 27412241, 2016). "There is also the effect mediated by IL-1, IL-6, IFNγ and TNFα, that increases the invasiveness of the tumor on bone tissue." (PMID 27821086, 2016). "Tumor necrosis factor alpha (TNFα) and interferon gamma (IFNγ) were originally identified to show potent anti-tumor activity and immunomodulatory capability." (PMID 27342639, 2016). "Another functional role of Tenascin-C is immune-modulatory; it inhibits the proliferation of blood lymphocytes in vitro and interferon-gamma production by tumor-infiltrating lymphocytes isolated from NSCLC specimens." (PMID 26967391, 2016). "PD-L1 is induced on tumor cells by tumor infiltrating lymphocytes releasing IFNγ as a method to limit tissue damage but which also restricts tumor immunotherapy." (PMID 27825115, 2016). "Concordantly, both TUNEL staining and immunofluorescence staining for cleaved caspase-3 revealed that TNFα or IFNγ increased the number of apoptotic cells inside the tumor while conjugation with TCP-1 further induced apoptosis." (PMID 27342639, 2016). "As also reported by others, IFNγ resulted in a strong up-regulation of PD-L1 expression on tumor cells." (PMID 27341020, 2016). "Ultimately, combination therapy led to reduced tumor growth, enhanced survival, increased IFNγ, tumor necrosis factor (TNFα), and Granzyme B within CD8+ T cells further supporting a mechanism of action non-redundant to established NCR blockade in clinic." (PMID 28031817, 2016). "Splenocytes from tumor-bearing mice that received C44 control antibody had a signal of 10.7 ± 1.7 when grown in media alone, and IFNγ production increased to 60.1 ± 4.8 spots per well with coculturing with irradiated E0771 cells." (PMID 27169467, 2016). "In contrast, adaptive resistance occurs in response to IFNγ produced by tumor-infiltrating T cells provoking PD-L1 upregulation on cells in the tumor microenvironment." (PMID 26910562, 2016). "Cellular immunity against the BCL1 tumor can enhance dormancy as suggested by the fact that interferon-gamma (IFN-γ) secreted by Th1 cells or cells of the innate immune system prolong immunity mediated by anti-Id antibody." (PMID 27959896, 2016). "The presence of tumor-specific, IFNγ-producing T-cells in CY+TLRa-treated mice prompted us to examine the development of immunological memory." (PMID 27341020, 2016). "We provide evidence for a co-regulated upregulation of genes encoding for HLA transcriptional regulators, peptide-loading machinery, and HLA proteins on the cell surface, which we attribute to the presence of tumor-infiltrating T cells, secreting IFNG." (PMID 27764126, 2016). "In line with our previous results regarding macrophage iron polarization, we observed a significantly reduced tumor cell proliferation upon incubation of tumor cells with LPS/IFNγ-stimulated MΦ supernatants." (PMID 27806101, 2016). "IFNγ is also a key molecule in IL-12-mediated anti-tumor activity, as IL-12 can stimulate the secretion of IFNγ by natural killer cells and T cells." (PMID 26799669, 2016). "In a revised model (V3), we assumed that the phenotype of tumor infiltrating lymphocytes progressively changes, as modeled by a decrease in cytotoxic killer function and IFNG production." (PMID 28101055, 2016). "In preclinical models, treatment with IMM-101 appeared to increase the secretion of IFNγ and cytotoxic mediators such as perforin and granzyme B at the tumor site, the draining lymph nodes and in the spleen in tumor-bearing mice." (PMID 27141395, 2016). "Greater numbers of IFNγ+ CD8+ cytotoxic T lymphocytes were also observed in the tumor microenvironment after RA190 treatment." (PMID 27655678, 2016).
tumor (continued). "Other cytokines are involved in such process like interferon gamma (IFN-γ) and IL-10 that are produced by tumour microenvironment." (PMID 26801617, 2016). "NK cell-derived IFNγ upregulates major histocompatibility complex class I molecules on tumor cells, rendering them sensitive to cytotoxic CD8+ T cells." (PMID 26716894, 2016). "Of particular interest was the low levels of IFNγ produced in the anti-PD-1 alone treated mice, even though they showed a good anti-tumor response." (PMID 27825115, 2016). "In tumor-bearing hosts adoptively transferred with both T and B cells, T cell production of IFNγ supported switching to the IFNγ-dependent IgG2a/c isotype." (PMID 27121060, 2016). "This means that the tumor-infiltrating lymphocytes (TILs), and especially the T cells as main producers of IFNG, are the ones triggering the increased HLA expression in UM." (PMID 27764126, 2016). "The purpose of these studies was to determine if relative MUC16 expression correlated with TNFα or IFNγ expression, independently of tumor stage or grade." (PMID 26918940, 2016). "Tumor-specific CD8+ T cell generation, associated with the secretion of Th1 cytokines (e.g., tumor necrosis factor α (TNFα) and interferon γ (IFNγ)), is desired in the context of anti-cancer therapy." (PMID 26993326, 2016). "Adoptive transfer of glycolipid-loaded CXCL16hi DCs enhanced IFNγ production and tumor control, while inducing less liver toxicity, compared to CXCL16neg DCs." (PMID 27471636, 2016). "Given the dependence of CY+TLRa treatment upon CD4+ and CD8+ T-cells as well as the requirement for IFNγ-producing T-cells for sustained tumor eradication, we inspected peripheral lymphoid organs for the presence of 4T1-specific T-cells." (PMID 27341020, 2016). "The ability of iNKT cells to promote a strong Th 1 response is critical for tumor control as iNKT cell-dependent protection from metastasis is lost in IFNγ−/− mice." (PMID 27471636, 2016). "The increased anti-tumor efficacy induced by MDSC-educated OT-1 cells correlated with a higher IFNγ production and an elevated frequency of the transferred CD8+ T cells in spleen and tumor." (PMID 27007050, 2016). "Accordingly, transferred-CD62L+ CD8+ T cells expanded in the presence of MDSC showed a higher accumulation in tumor and spleen and had an elevated IFNγ production, compared to the counterpart groups of transferred CD8+ T cells." (PMID 27007050, 2016). "Elevated PD-L1 expression as a tumor immune evasion mechanism to suppress the activity of tumor-infiltrating, IFNγ-producing T cells was also demonstrated in humans." (PMID 26910562, 2016). "In this context, IFNG is thought to be critical in regulating MHC class I protein expression by tumor cells." (PMID 28101055, 2016). "Interferon-gamma (IFN-γ) is one of the most important cytokines that natural killer cells secrete to perform their defense duty in tumor immunity and against microbe invasion." (PMID 26758620, 2016). "After 24 h treatment, TCP-1/IFNγ induced more MHC-I expression inside the tumor than control or IFNγ, indicating more IFNγ was accumulated in the tumor by targeted delivery by TCP-1 peptide." (PMID 27342639, 2016). "Both had a reduced expansion in IL-17−/− mice, and were enhanced in IFNγ−/− mice as a consequence of an elevated intra-tumor IL-17 level." (PMID 27589729, 2016). "On the other hand, it is possible that tumor growth was not reduced because some cytokines, like the more DMSO sensitive G-CSF and IFNγ, were inhibited and this reduced the ability of the immune system to restrain tumor growth." (PMID 27031833, 2016). "In these mice, intact transactivation of NK cell IFNγ responses was likely sufficient to mediate tumor control." (PMID 27471636, 2016). "The T cells then differentiate into Th1-type cells making high levels of IFNγ, which we identified as a major mediator of tumor control." (PMID 27121060, 2016).
tumor (continued). "Several published studies also indicate that the PD-L1 level within the tumor environment can be elevated by infiltrating activated T cells secreting IFNγ." (PMID 27825115, 2016). "Interferon gamma (IFNγ) and IL-10 are considered hallmark cytokines for antitumour TH1 responses and immunological tumour tolerance, respectively." (PMID 27990285, 2016). "This surge of cytokine release, including IFNγ, has a potent effect on PD-L1 expression which in turn dampens the full potential of BRAFi on anti-tumor immunity." (PMID 26943572, 2016). "IFNγ secreted by NK cells has numerous effects on tumor cells, including activation of macrophages, up-regulation of class I expression by antigen presenting cells (APC), polarization of type 1 T-helper cell (Th1), and direct anti-proliferative activity." (PMID 27816971, 2016). "In order to define the functional consequences of MΦ-polarization in terms of iron sequestration versus release, we checked the proliferation rate of tumor cells, which were stimulated with supernatants of LPS/IFNγ- or IL-10-treated MΦ." (PMID 27806101, 2016). "Taken together, our results suggested that deletion of IL6 promoted HCC development and increased tumor burden, NK cells, TNFα and IFNγ were significantly reduced in tumors of DDB1F/F, Alb-Cre+/−, IL6−/− mouse." (PMID 27556180, 2016). "To test if the co-culture is a valid system to investigate CTL–tumor cell interactions, we analyzed two markers whose behavior is known to change upon exposure to IFNγ or CTLs: HLA-DR and HLA Class I." (PMID 27625650, 2016). "We used the dose of 1 μg/mouse for TNFα and TCP-1/TNFα and 5 μg/mouse for IFNγ and TCP-1/IFNγ according to previous experiment which indicated that 5 μg TCP-1/IFNγ can induce maximal anti-tumor effect." (PMID 27342639, 2016). "We further demonstrate that P2Et-treated tumor cells are highly immunogenic in vaccinated mice and induce immune system activation, clearly shown by the generation of interferon gamma (IFN-γ) producing tyrosine-related protein 2 antigen-specific CD8+ T cells." (PMID 27253407, 2016). "Statins potentiate IFNγ-induced MHC class I expression in tumor cell lines but reduce both basal and inducible expression in primary muscle cell line." (PMID 27907087, 2016). "Activation of Cysteine-rich 61 protein (CCN1) also inhibited the oncolytic virus anti-tumor efficacy in glioblastoma through activation and infiltration of inflammatory TAMs and NK cells expressing IL-1β, IFNγ, CXCL10, and MCP-1/3." (PMID 28536380, 2016). "These experiments implicate an important role for CXCR6/CXCL16 interactions in regulating iNKT cell IFNγ production and tumor control." (PMID 27471636, 2016). "One study showed that T cells from tumor-bearing mice exhibited decreased IFNγ production that correlated with expression of distinct NF-κB/Rel isoforms, suggesting that NF-κB signaling influences T cell effector function in antitumor immune responses." (PMID 27314056, 2016). "Both pathways of tumor cell recognition trigger NK cells to secrete cytokines such as IFNγ, and release cytolytic proteins including perforin and granzymes, that induce tumor cell death through the activation of an apoptotic cascades." (PMID 26928328, 2016). "The proportion of DCT-specific T cells is not reduced relative to the global number, but the remaining DCT-specific T cells are dysfunctional in their ability to secrete IFNγ in response to tumor antigen." (PMID 27196057, 2016). "Further we show that the frequency of cytokine producing (IFN-γ) CD8+ and CD4+ T cells detected in the spleen was higher in Gel + OVA vaccinated mice than others, implying an IFNγ-mediated anti-tumour effect." (PMID 27756214, 2016). "Experimentally, the expression of genes associated with T cells (TCRa) and the secretion of cytokines related to their biological function (IFNG and TNFα) were measured in samples obtained from homogenized tumor samples." (PMID 28101055, 2016).